NPM2 (nucleophosmin/nucleoplasmin 2)
Description:
Core histones chaperone involved in chromatin reprogramming, especially during fertilization and early embryonic development. Probably involved in sperm DNA decondensation during fertilization.
Tractability: No criterion of Open Targets' tractability assessment is met for any kind of drug.
Gene: Protein-coding gene on chromosome 8 (22,024,125 to 22,036,897, forward strand). Ensembl gene ENSG00000158806.
Subcellular location: Nucleus
Subcellular location (Human Protein Atlas): Nucleoli; Nucleoplasm
Pathways (Reactome):
Developmental Biology: Replacement of protamines by nucleosomes in the male pronucleus
Gene Ontology:
Molecular function: protein binding; chromatin binding; histone binding; RNA binding; enzyme binding; identical protein binding
Biological process: blastocyst development; chromatin remodeling; oocyte differentiation; positive regulation of meiotic nuclear division; regulation of exit from mitosis; single fertilization; chromatin organization; positive regulation of DNA metabolic process; positive regulation of DNA replication
Cellular component: chromatin; nucleus; cytoplasm; nucleolus; nucleoplasm
Genetic constraint (gnomAD): Loss-of-function variants: 22 observed, 30.75 expected, observed/expected ratio (o/e) 0.72, 90% interval 0.51 to 1.02. The upper end of that interval is the gene's LOEUF score, 1.02, which puts it in group 4 of 6, group 1 being the genes least tolerant of losing a copy. Missense variants: 281 observed, 266.32 expected, observed/expected ratio (o/e) 1.06, 90% interval 0.96 to 1.16. Synonymous variants: 111 observed, 95.78 expected, observed/expected ratio (o/e) 1.16, 90% interval 0.99 to 1.36.
Homologues: Orthologues: chimpanzee NPM2 (99% identical), rabbit NPM2 (71% identical), dog NPM2 (70% identical), mouse Npm2 (65% identical), rat Npm2 (62% identical), guinea pig NPM2 (53% identical), tropical clawed frog npm2 (45% identical), zebrafish npm2b (34% identical), Drosophila melanogaster Nph (21% identical), Drosophila melanogaster Nlp (21% identical). Paralogues in human: NPM1 (32% identical), NPM3 (30% identical).
Diseases named in the same sentence as NPM2 in open-access papers:
NPM2 is named in the same sentence as 17 diseases in open-access papers, as found by Europe PMC text mining. Sharing a sentence is not in itself a finding about the gene and the disease. The quoted sentences say what the papers report.
melanoma (6 papers, 2016 to 2025). A malignant, usually aggressive tumor composed of atypical, neoplastic melanocytes. "The results showed that there was a significant loss of NPM2 protein expression in malignant melanoma cells." (PMID 36280841, 2022). "Among these genes, we found that the loss of NPM2 could be a candidate immunohistochemical marker for differentiation of melanoma and melanocytes." (PMID 30719424, 2018). "NPM2 is also regarded as a potential immunohistochemical marker via making a distinction between melanoma and benign 5 melanocytic lesions." (PMID 33777092, 2021). "In many normal melanocytes, NPM2 showed distinct immunohistochemical staining, while its expression was lost in malignant melanoma cells." (PMID 30719424, 2018). "Our analysis indicated that the NPM2 locus was far more hypermethylated in melanomas as compared to that in normal melanocytes." (PMID 30719424, 2018). "Subsequent studies revealed that NPM2 was hypermethylated and downregulated in melanomas, which was consistent with previous reports." (PMID 30719424, 2018). "In this study, we found a significant difference in NPM2 staining property between normal pigment cells and malignant melanoma cells." (PMID 30719424, 2018). "NPM2 was observed in only five melanoma samples (15.6%, 5/32; P = 0.001) while most of the archived melanocyte samples displayed NPM2 staining (74.6%, 50/67)." (PMID 30719424, 2018). "TNFAIP2 (tumor necrosis factor, alpha-induced protein 2) was also found to be hypermethylated in colorectal cancer and NPM2 (nucleophosmin/nucleoplasmin 2) in melanoma and acute myeloid leukemia." (PMID 26646589, 2016). "NPM2 is hypermethylated and downregulated in melanomas, thus, it might be involved in the early events in the development of malignant melanoma." (PMID 33777092, 2021). "Moreover, we confirmed the downregulation of NPM2 mRNA expression in melanoma cells by expression microarray and real-time PCR, and the results were consistent with a previous report." (PMID 30719424, 2018). "It is suggested that NPM2 levels may decrease with malignant transformation and it may be involved in the early events in the development of malignant melanoma." (PMID 30719424, 2018). "In addition, NPM2 immunoreactivity could be used to differentiate melanomas from normal melanocytes or benign disease." (PMID 30719424, 2018). "Based on this, we hypothesized that NPM2 could be a clinical marker for diagnosing melanoma." (PMID 30719424, 2018). "Promoters of COL1A2, HSPB6, NPM2, MT1G or DDIT4L were identified as hypermethylated in melanoma cells suggesting that they can be used as predictors for melanoma progression." (PMID 40427015, 2025). "Therefore, NPM2 protein expression could distinguish malignant melanoma from normal melanocytes." (PMID 36280841, 2022). "The results were validated by bisulfite sequencing of COL1A2, NPM2, HSPB6, DDIT4L, and MT1G promoters, which exhibited increasing incidence with advanced melanoma stage, suggesting potential use as predictors of melanoma progression." (PMID 28396701, 2017). "Immunostaining with NPM2 antibody showed clear positive findings in the nucleus of melanocytes, but nuclei of malignant melanoma cells showed no staining." (PMID 30719424, 2018). "Thus, negative NPM2 immunostaining may be an effective clinical marker to distinguish melanomas from benign melanocytic lesions, and may be a target for epigenetic manipulation in the future." (PMID 30719424, 2018).
breast carcinoma (1 paper, 2025). "Subsequently, we further narrowed down the eight candidate genes (TRIM47, SPHK1, RGMA, ROPN1B, LARP6, ROPN1, NPM2 and LPL) that are shared in TNBC compared to ER+ and HER2+ breast cancer subtypes in cancer cells." (PMID 40635123, 2025).
breast tumour (1 paper, 2008). "Since NPM2 and FGF17 were over-expressed in two cancer cell lines, expression levels were analysed in 61 primary tumours, from the primary breast tumour series analysed by FISH, for which cDNA was available." (PMID 18840272, 2008).
leukemia (1 paper, 2011). A malignant (clonal) hematologic disorder, involving hematopoietic stem cells and characterized by the presence of primitive or atypical myeloid or lymphoid cells in the bone marrow and the blood. "DPYS, NPM2, OSCP1, PDLIM4 and TFAP2E genes were found hypermethylated, and CDKN2B (p15INK4B) homozygously deleted in the K562 leukemia cell line." (PMID 21760961, 2011).
mesothelioma (1 paper, 2022). A usually malignant and aggressive neoplasm of the mesothelium which is often associated with exposure to asbestos. "Among mesothelioma patients, 5-year survival of patients with low-NPM2-expression was significantly higher than that of the high-NPM2-expression patients." (PMID 35490253, 2022).
pleura mesothelioma (1 paper, 2022). "However, a 5-year survival of pleura mesothelioma patients with low-NPM2 expression was higher than that of the high-NPM2-expression pleura mesothelioma patients, a result different from our current study." (PMID 36280841, 2022).
vascular tumor (1 paper, 2022). "NPM2 expression level was negatively correlated with the following three clinicopathological factors: CC score, vascular tumor emboli, and SAEs." (PMID 36280841, 2022). "NPM2 expression level was independently negatively correlated with the vascular tumor emboli." (PMID 36280841, 2022). "It is particularly noteworthy that the level of NPM2 expression was independently negatively correlated with the vascular tumor emboli, indicating that NPM2 could help evaluate the biological behavior of MPM." (PMID 36280841, 2022). "Our study showed that the expression level of NPM2 protein was negatively correlated with PCI score, CC score, vascular tumor embolic, and SAEs." (PMID 36280841, 2022). "Univariate analysis showed that NPM2 protein expression was negatively correlated with the following 4 clinicopathological factors: PCI score (χ2 = 4.216, P = 0.040), CC score (χ2 = 4.895, P = 0.027), and vascular tumor emboli (χ2 = 7.481, P = 0.006), SAEs (χ2 = 4.285, P = 0.038)." (PMID 36280841, 2022).
tumor (4 papers, 2008 to 2023). "Three tumours expressed NPM2 at a higher level than any of the commercial controls, although at a lower level than the normal luminal and basal cells." (PMID 18840272, 2008). "For example, the histone chaperone nucleoplasmin (Npm2) has been identified as a putative nuclear size effector that binds histones and may play a key role in tumor development and progression." (PMID 38001682, 2023). "Our study suggested that 76.1% of patients lacked NPM2 protein expression with poor prognosis, suggesting that NPM2 may be a tumor suppressor gene in MPM." (PMID 36280841, 2022). "NPM2 expression level was independently negatively correlated with the vascular tumor emboli, indicating that NPM2 could help evaluate the biological behavior of MPM." (PMID 36280841, 2022). "A total of 76.1% of patients lacked NPM2 protein expression with poor prognosis, suggesting that NPM2 may be a tumor suppressor gene." (PMID 36280841, 2022).
NPM2 also shares sentences with these, for which no sentence is quoted: cancer (3 papers); malignant peritoneal mesothelioma (2); acute myeloid leukemia (1); adrenocortical carcinoma (1); colon adenocarcinoma (1); colorectal cancer (1); glioblastoma multiforme (1); testicular germ cell tumor (1); thymoma (1).